STAT3 (signal transducer and activator of transcription 3)
Diseases named in the same sentence as STAT3 in open-access papers (continued):
Sharing a sentence is not in itself a finding about the gene and the disease.
tumor (continued). "For example, nanoparticles (NPs), due to an enhanced permeability and retention (EPR) effect, may enhance STAT3 inhibitor tumor targeting." (PMID 35158821, 2022). "In contrast, the combination of STAT3 inhibitors with PD-L1 inhibitors has been shown to promote PD-L1 expression and suppress the immune response instead, which leads to the reduction in the anti-tumor effect of the anti-PD-L1 antibody." (PMID 35158821, 2022). "Dysregulation of the STAT3 gene promotes tumor growth as well as metastasis of cancer cells." (PMID 35682652, 2022). "Moreover this study reported that STAT3 inhibition in CD4+ lymphocytes improved the anti-tumor immunity conferred by a lymphocyte adoptive transfer." (PMID 35606804, 2022). "Finally, immunohistochemistry demonstrated that MTCAFs can activate AKT and STAT3 signaling pathways in tumor tissues in nude xenograft tumor models." (PMID 36016615, 2022). "Because STAT3 regulates tumor progression, we next verified whether STAT3 was involved in MAL-mediated inhibition of the EMT in GC cells." (PMID 35093120, 2022). "Further, the results of Western blot and ELISA demonstrated that the Erlotinib treatment led to increased levels of APE1, IL‐6 and p‐STAT3/STAT3 in tumour tissues, which could further be increased in response to HCC827R‐CSC‐EVs (all p < .01)." (PMID 35605028, 2022). "In sum, these studies suggest that TAM-associated tumor cell proliferation occurs in an IL-6 or IL-10/STAT3 signal cascade dependent manner and targeting proteins in the IL-6 or IL-10/STAT3 signaling pathway to attenuate tumor cell proliferation is promising in anti-tumor therapies." (PMID 35327584, 2022). "While tumor cell sensitization may be a result from multiple mechanisms, these results stress the benefit of combining immunotherapy with STAT3 inhibition." (PMID 36124553, 2022). "We found that STAT3-Y705F and shFOXM1 alone or in combination could inhibit the growth of icotinib-resistant xenograft tumours." (PMID 35690866, 2022). "Moreover, activation of the NF-κB pathway and signal transducer and activator of transcription 3 (STAT3)/p38 signaling stimulated by NETs is another proposed mechanism of promoting tumor proliferation in DLBCL." (PMID 36384979, 2022). "Upon binding to its receptors, IL-6 triggers the pathway and activates downstream molecules, such as STAT1 and STAT3, which may enhance the capacity of tumor cells to survive in a highly inflammatory environment and impair immunotherapy effects." (PMID 36119033, 2022). "Correspondingly, STAT3 was reported to modulate hypoxia-induced mechanisms in other tumor entities." (PMID 35326623, 2022). "However, the synergistic combination of anti-PD-1 therapy and the natural STAT3-inhibiting compound curcumin augmented anti-tumor responses in a colon carcinoma model." (PMID 35053592, 2022). "We observed significantly reduced SA14 and increased STAT3 expression levels in the tumours compared to their corresponding adjacent normal (paracancerous) tissues and a substantial inverse association between the levels of SA14 and STAT3 expression in tissues." (PMID 35858011, 2022). "Therefore, we concluded that IL-6 upregulated expression of PD-L1 in tumor via the JAK1/Stat3 signaling pathway." (PMID 35550592, 2022). "Moreover, syntenin and STAT3 interactions have been observed in various cancers, and the syntenin/STAT3 pathway can promote tumor invasion and metastasis." (PMID 35756080, 2022). "The finding that the JAK2/STAT3 pathway could be blocked by excessive ROS was consistent with the tumor-related reports, but contrary to the conclusions of some inflammation-related studies." (PMID 35116094, 2022). "In a recent study, the authors showed that a potent and selective small-molecule degrader of STAT3 could produce complete tumor regression." (PMID 36221123, 2022).
tumor (continued). "JAK2/STAT3 signaling pathway, which is extremely related to cancer initiation, metastasis, progression, chemoresistance, and immune evasion, is assumed to be a central mediator of tumor-related immune suppression." (PMID 35606804, 2022). "Also, increased STAT3 activity in CD11b+myeloid cells, motivates the local invasion of primary tumor cells into the blood or lymphatic vessels to move towards the metastatic sites and create pre-metastatic niche." (PMID 35965504, 2022). "Signal transducer and activator of transcription 3 (STAT3) is constitutively activated in various cancers and plays a pivotal role in regulating all of these processes and thereby mediates the crosstalk between the tumor microenvironment and immune cells." (PMID 35865518, 2022). "IL-6/STAT3 signaling is required for the maintenance of breast CSCs and tumor growth." (PMID 36010693, 2022). "However, the mechanism by which upstream signals regulate the transcriptional expression of STAT3 in DCs recognizing tumour antigens, especially GSC antigens, remains poorly understood." (PMID 36157880, 2022). "Another group, using an adenoviral Cre model, observed a tumor suppressor function for STAT3." (PMID 35406557, 2022). "Bcl-XL mediated expression and apoptosis of various tumor cells are regulated by STAT3 and STAT5." (PMID 35401182, 2022). "The siRNA-loaded CL4H6-LNPs exhibited strong blood circulation stability and high tumor-specific accumulation, which induced an antitumor response by silencing two targeted genes, STAT3 and HIF-1α, both of which were found to be increased in TAMs and to promote protumorous functions." (PMID 35183252, 2022). "STAT-3 may be activated by tyrosine phosphorylation in response to several cytokines signals, contributing to tumor proliferation and survival, thus representing a promising direct target for novel anticancer therapies." (PMID 35887090, 2022). "Furthermore, constitutive phosphorylation of STAT3 in tumor tissue is closely correlated with a poor prognosis in HCC patients." (PMID 35563493, 2022). "In addition, autophagy can also influence tumor progression by regulating the phosphorylation level of STAT3, although it has only been investigated in a limited number of studies." (PMID 35559037, 2022). "CD123 expresses on macrophages in the microenvironment of HL, suggesting that CD123-targeted therapies might impact on the tumor microenvironment.It was previously shown that TAMs can activate HL cell proliferation through the STAT3 pathway." (PMID 35875135, 2022). "Moreover, CRC exhibits constitutive activation of NF-κB and STAT3, transcription factors that influence interactions between tumor cells and tumor microenvironment and play integrated roles in cancer-promoting inflammation." (PMID 36499154, 2022). "Regardless of at hypoxia or at normoxia, tanshinone I subdued angiogenesis in epithelial cells (HMEC-1) and the secretion of VEGF from tumor cells (MCF-7) by the common mechanism: deduction of p-STAT3 and HIF-1α, and also inhibited VEGF against lung carcino-angiogenesis." (PMID 35784750, 2022). "Stat3 signaling interacts with other signaling pathways to confer stability for tumor progression." (PMID 36454780, 2022). "STAT3 may be a negative regulator of certain cancer types, and therapies targeting STAT3 may therefore need to consider the origin of the tumor type." (PMID 36231093, 2022). "Thus, IL-6 induces the activation of its downstream cascade JAK2/STAT3 pathway, contributing to tumorigenesis by regulating cell cycle progression, angiogenesis and tumor cell escape of the immune system." (PMID 36591515, 2022). "Furthermore, STAT3 has been shown to be involved in the formation of immunosuppressive tumor microenvironments (TMEs) via regulating not only immune cells but also cancer-associated fibroblasts (CAFs) and endothelial cells." (PMID 36010693, 2022). "STAT3 is believed to promote a pro-metastatic environment for the tumor cells to flourish." (PMID 35505937, 2022).
tumor (continued). "In addition, IL6 produced by inflammatory and tumor cells is able to induce POSTN production by CAFs via STAT3 signaling." (PMID 35567669, 2022). "It should be mentioned that 40% of our patients had NAFLD, which might influence the results slightly since NAFLD promotes STAT3 in tumor cells mediated through effector and helper T cells which might promote cancer initiation." (PMID 34585256, 2022). "STAT3 regulates cancer suppressor genes and oncogenes and influences tumor microenvironments." (PMID 36061200, 2022). "STAT3 is activated in tumor cells, resulting in overexpression of the downstream target genes." (PMID 35810312, 2022). "Consequently, combination-based therapeutic approaches utilizing both MEK and STAT3 inhibitors have been tested and led to reduced tumor growth and increased survival in preclinical animal models." (PMID 35835937, 2022). "Furthermore, the genetic ablation of Stat3 in the hematopoietic cells shows significant regression of primary tumor growth and the suppression of metastasis." (PMID 35053592, 2022). "STAT3 activation contributes to a highly immunosuppressive tumor microenvironment due to increased secretion of IL-10 and TGFβ, negative regulation of neutrophils, NK cells, effector T cells, and DCs and positive regulation of Treg cells and myeloid-derived suppressor cells (MDSCs)." (PMID 36614001, 2022). "Moreover, APN upregulation also impedes STAT3 signal pathway activation, which in turn is unable to endorse angiogenesis and invasion and incapable of evading anticancer immunity, hence blocking tumor progression." (PMID 35681689, 2022). "Meanwhile, microRNAs could also inhibit epithelial–mesenchymal transition (EMT) and reverse drug resistance by inhibiting the STAT3 signaling pathway, thereby suppressing tumor growth and improving the therapeutic effect of chemotherapeutic drugs." (PMID 36559280, 2022). "Moreover, FLU also decreased the level of myeloid-derived suppressor cells (MDSC) and STAT3 in tumor tissues." (PMID 35008943, 2022). "Looking into the expression of SMG1, IL6ST (IL-6 signal transducer) and STAT3 in single tumor cells from those datasets, we observed that higher expression of SMG1 co-localized in the same cells that had higher levels of IL6ST, being such association very strong with the STAT3 factor as well." (PMID 36443756, 2022). "In order to investigate whether Stat3-dependent miR-21 regulation contributes to Stat3-dependent tumor formation, we exploited the Gp130F/F mouse as a clinically relevant model of intestinal-type gastric cancer." (PMID 35053428, 2022). "PD-1 in exhausted T cell promotes FAO to restrain anti-tumor response by upregulating STAT3 signaling pathway, which could be recovered by STAT3 signaling inhibitors and FAO inhibitors." (PMID 36618408, 2022). "Mc-1Stat3 treatment is more efficient in decreasing tumor growth and lung metastasis area compared with dc-Stat3 treatment, which is consistent with the higher biostability of mc-1Stat3 compared with dc-Stat3 observed in TNBC cells treated in vitro." (PMID 35847174, 2022). "Based on these data, STAT3 may also play a tumor suppressor role and promote different functions depending on the tumor stage described for STAT1." (PMID 35207527, 2022). "Thus, STAT3 overexpression was induced in PANC-1 cells using lentiviruses to reevaluate the effect of activated STAT3 on the anti-tumor effect of Stattic." (PMID 35288541, 2022).
tumor (continued). "Top canonical pathways associated with recovery were Signal Transducer and Activator of Transcription 3 (STAT3) Pathway, Tumor Microenvironment Pathway, Regulation of the Epithelial Mesenchymal Transition by Growth Factors Pathway, and Acute Phase Response Signaling." (PMID 35928129, 2022). "Activated STAT3 mediates the expression of various genes in response to cell stimuli, thus playing a key role in cellular processes such as tumor cell growth, proliferation, survival, resistance to chemotherapeutics, and dysregulation of energy metabolism in CML." (PMID 36033954, 2022). "Moreover, the immunohistochemical expression of STAT3 in tumor-infiltrated areas is nearly three times higher than that in tissues selected from adjacent non-tumor regions." (PMID 35249109, 2022). "The JAK2/STAT3 and PI3K/Akt pathways may play a major role in cancer angiogenesis, especially the latter, which is also implicated in tumor metastasis and invasion." (PMID 35984196, 2022). "JAK-STAT signaling is highly active in CSCs, and studies have reported that activation of STAT-3 by IL-6 has a profound effect on tumor initiation and progression, invasion and metastasis by protecting tumor cells from apoptosis, driving epithelial–mesenchymal plasticity, and enhancing angiogenesis." (PMID 36466926, 2022). "IL-6 and the IL-6/JAK/STAT3 signalling pathway have a key role in the growth and development of many human cancers, and have been shown to drive cellular proliferation, survival, invasiveness, and metastasis of tumour cells." (PMID 36396670, 2022). "Interestingly, the GFP signal was observed in the tumor spheroids introduced with the STAT3 reporter system." (PMID 36359204, 2022). "One early activated URM is RAF1, a known oncogene but which is also capable of tumor suppressant activity related to decreased IL-6 and JAK/STAT3 signaling activity, and simultaneous IL-6 and STAT3 activation has been shown to promote tumor formation in gastrointestinal tissues." (PMID 34983392, 2022). "Also, an adequate balance between STAT1 and STAT3 is very crucial for shaping the fate of macrophage polarization and tumor progression." (PMID 34689394, 2022). "Interestingly, IL6/STAT3 signaling has been shown to play a role in tumor progression by inducing epithelial to mesenchymal transition and angiogenesis." (PMID 35327992, 2022). "Mechanically, EZP6438 could reduce the H3K27me3 level on the promoter of STAT3 to induce upregulation of pro-inflammatory cytokines to exert anti-tumor effects." (PMID 35432300, 2022). "Meanwhile, the infiltration of TAMs is associated with resistance to chemotherapy in colorectal cancer (CRC), and TAM-derived IL-6 inhibits the expression of tumor suppressors by activating the IL6R/STAT3 pathway, thereby inducing drug resistance in cancer cells." (PMID 36510315, 2022). "STAT3 is considered a major driver of immune evasion and tumor progression." (PMID 36556226, 2022). "Moreover, decreased p-STAT3 expression in tumor tissues derived from anti-miR-130b-3p-expressing NTC/T2 null was partially rescued by knockdown of MBNL1." (PMID 36217202, 2022). "In addition, some transcription factors like signal transducer and activator of transcription 3 (Stat3) were initially identified as oncogenes in tumour cells." (PMID 35170261, 2022). "Targeting IL-6R and IL-11R in mouse models can significantly reduce STAT3 activation and enhance the effect of chemotherapy agents such as gemcitabine in tumor killing effect, suggesting that the interleukin pathway may be a good therapeutic target." (PMID 35965504, 2022). "Importantly, vast evidence indicates the direct involvement of STAT3 in driving PD-L1 and PD-L2 expression in tumor cells." (PMID 35865518, 2022). "STAT3 promotes the differentiation and expansion of MDSCs, thereby enhancing their ability to suppress effector T cells and promote the differentiation of Treg cells, which enable the augmentation of tumor formation." (PMID 36010693, 2022).
tumor (continued). "CXCR4 enhances tumor blood vessel formation within gastric carcinoma through JAK2/STAT3 activation." (PMID 35123491, 2022). "In addition, our mouse model indicated that overexpression of STAT3 promoted tumor proliferation by activating YAP signaling." (PMID 35885009, 2022). "Moreover, studies in mice, including gene knock-out and transposon hopping screens, also corroborated RPTPρ as tumor suppressive and molecular studies highlighted paxillin and STAT3 as relevant substrates." (PMID 36755664, 2022). "In addition, the IL-23/STAT3/IL-17 axis plays an important role in tumor progression and inflammation." (PMID 36098359, 2022). "Similarly, siRNA specific for the SH2 domain of STAT3 have been designed that have shown promising antitumor effects in prostate cancer cells and patient-derived murine xenograft tumor models." (PMID 35401182, 2022). "Moreover, the STAT3/epigenetic kinase mitogen- and stress-activated protein kinase 1 signaling significantly promotes GC cell proliferation and tumor growth of xenografts." (PMID 36443287, 2022). "IL-10 acts to promote tumor growth through the JAK2/STAT3 pathway." (PMID 36338705, 2022). "These anti-inflammatory effects targeting transcription factors STAT3 and NF-κB and cytokine IL-6 on macrophage might contribute to the anti-tumor immune microenvironment by blocking the polarization of macrophages into M2." (PMID 35890318, 2022). "STAT3 is considered as a driver of an immune suppressive tumor microenvironment." (PMID 35865518, 2022). "The first was inflammation-related pathways, such as the IL6/JAK/STAT3 signalling, inflammatory response, IL2/STAT5 signalling, TNF-alpha signalling via NFKB, and KRAS signalling pathways, which have been proven to be associated with tumours." (PMID 35246158, 2022). "Likewise, LLL-3, an early generation STAT3 inhibitor, has shown similar antitumor activity in different tumor models." (PMID 35401182, 2022). "Our findings suggest that CDCA may enhance the anti-tumor effects of sorafenib via inhibition of the EGFR/Stat3 signaling pathway." (PMID 35252007, 2022). "Herein, it may be effective for decreasing tumor chemotherapy resistance via targeting TAMs and related IL-6/STAT3 signaling pathways." (PMID 35193986, 2022). "STAT3 has been implemented in immune escape and the promotion of tumor proliferation." (PMID 36031601, 2022). "In addition, NF-kB and STAT3 are also common factors in tumor severity, and in the process of inflammation discovery, TNF-α and IL-1 were found to promote the pro-inflammatory phenotype of endothelial cells and fibroblasts by activating the NF-kB pathway." (PMID 36686745, 2022). "In this study, we first reported that liensinine could suppress the activation of the JAK2/STAT3 pathway in tumor cells." (PMID 35116094, 2022). "Because there is no specific drug for late-stage HNSCC, the PROTAC-based approach may afford a new treatment option by inducing the total degradation of STAT3 protein, thus inhibiting tumor recurrence and metastasis." (PMID 36509291, 2022). "In addition, STAT3 signaling was critical in spheroid formation on polymer X. Our PTF platform allows the efficient generation of tumor spheroids from cancer cells, thereby overcoming the existing limitations of cancer research." (PMID 36359204, 2022). "Wu78 found that IL-17 could promote tumor angiogenesis by mediating the up-regulation of VEGF in GC through STAT3 pathway." (PMID 35610340, 2022). "Recent studies have shown that the STAT3 signaling pathway promotes tumor fatty acid metabolism." (PMID 35574370, 2022). "In addition, it was demonstrated that STAT3 activation in type VI collagen-expressing fibroblasts promoted tumor development in experimental in vivo models of CRC." (PMID 35326623, 2022). "In addition, CHE can mediate tumor cell death through ROS-dependent endoplasmic reticulum (ER) stress and STAT3 inactivation." (PMID 35721116, 2022).